MYC (MYC proto-oncogene, bHLH transcription factor)
Diseases named in the same sentence as MYC in open-access papers (continued):
Sharing a sentence is not in itself a finding about the gene and the disease.
tumor (continued). "Our results revealed that SLC7A1 regulates multiple signaling pathways involved in tumor proliferation, including E2F targets, G2M checkpoint, and MYC targets." (PMID 41184266, 2025). "MYC’s influence on integrin expression creates a feedback loop in which integrin-mediated signaling enhances MYC activity, further exacerbating tumor progression." (PMID 40076599, 2025). "Inactivation of MYC can lead to sustained tumor regression and increased radiosensitivity, whereas its overexpression promotes radioresistance by driving EMT, tumor angiogenesis, and invasion." (PMID 40244089, 2025). "Dysregulation of MYC not only drives tumor growth but also promotes angiogenesis and immune evasion, thereby altering the tumor microenvironment." (PMID 41155227, 2025). "Amplification or overexpression of proto-oncogenes, such as MYC and cyclin D1, can also promote tumor growth and relapse by facilitating cell cycle progression and genomic instability." (PMID 39934876, 2025). "An analysis of 33 different tumor types within the TCGA database also indicated a significant association between FAM111B and the MYC pathway in the majority of tumors (28/33) (P < 0.05)." (PMID 40781291, 2025). "C2 displayed amplifications in MYC and NOTCH2, potentially linked to aggressive tumor phenotypes, along with deletions in RB1 and CSMD1, which are associated with tumor suppressor loss." (PMID 41568381, 2025). "MYC also modulates the tumor microenvironment, in part through its influence on angiogenic factors, allowing the tumor to sustain its growth and invasion." (PMID 40076599, 2025). "Pathway enrichment analysis showed C3 is lowest in DNA repair and MYC targets compared with other MSig subtypes, indicating C3 is relatively stable during tumour growth and proliferation." (PMID 41292185, 2025). "hnRNPAB enhances CXCL8‐dependent neutrophil recruitment by prolonging the half‐life of MYC mRNA in metastatic tumor cells." (PMID 40027151, 2025). "The BET inhibitor JQ1, along with analogs such as I-BET151 and OTX015, initially showed robust preclinical efficacy by dramatically downregulating MYC expression, resulting in significant tumor growth inhibition across diverse cancer models." (PMID 40365020, 2025). "Although the trial included many MYC-dependent tumor types in which CDK9 acts as a central focus in the oncogenic transcriptional regulatory network, this report focuses on the treated ACC subgroup." (PMID 40277179, 2025). "Based on the transcriptomics data, we generated the spatial expression mapping of HGF (stroma-enriched), MET, and MYC (tumor-enriched), and confirmed their co-localization within High-M CRC regions bordering mCAFs." (PMID 41234356, 2025). "ATF4 and c-MYC activation induced by EIF1AX mutations enhance amino acid transporter expression and increase mTOR sensitivity to amino acid availability, promoting tumor growth." (PMID 40363930, 2025). "Single-cell RNA-seq analysis of 1163 human tumor samples covering 24 tumor types shows that hypoxia, together with MYC gene clusters are the two of the most commonly recurring transcriptional programs in heterogenous tumors." (PMID 40326560, 2025). "In this case, downregulated pathwayswere associated with SMARCA2 targets, epigenetic changes, metastasis,AKT targets, Hedgehog signaling, MYC targets, tumor evasion, and livercancer." (PMID 40821580, 2025). "The tumor-bearing mice treated with the c-MYC drugs (3.6 μg) show a significant reduction in the tumor volume (*p = 0.019) compared to the controls, with a tumor volume reduction of approximately half." (PMID 40949131, 2025). "In non-small cell lung cancer (NSCLC), USP36 enhances KHK-A expression through the c-MYC-hnRNPH1/H2 axis, thus promoting tumor growth primarily by boosting glycolysis." (PMID 40520908, 2025).
tumor (continued). "MYC signaling is well acknowledged to be involved in tumorigenesis, tumor metastasis, and the EMT process." (PMID 40727938, 2025). "Among the identified clusters, cluster 1 demonstrated high proliferative capacity and elevated expression of MYC and proliferation-related genes, which appears to be a primary driver of tumor vascular abnormalities." (PMID 40303332, 2025). "WEE1 kinase inhibition represents another strategy for exploiting replication stress in rapidly proliferating tumours, and recent studies have begun to uncover how MYC modulation interacts with the WEE1 DNA repair pathway." (PMID 41561634, 2025). "The circular PA1-ProMyc chimeras achieved tumor regression in xenograft tumor models, laying the foundation for the clinical development of effective MYC degraders." (PMID 40290126, 2025). "Recent studies have found that IGF2BP1 can enhance the expression of MYC, a vital oncogene highly expressed in cancers, by promoting m6A methylation-mediated mRNA stability, thereby accelerating tumor cell growth." (PMID 40584294, 2025). "In cancer, FBXW7 plays a critical role in modulating the tumor immune microenvironment by inhibiting macrophage M2 polarization through the targeted degradation of c-MYC." (PMID 40534867, 2025). "Given the complexity of MYC's upstream regulatory work 70, it is likely that there exist additional, miR-218 independent mechanisms of MYC regulation in promoting tumor growth." (PMID 40303332, 2025). "In the normal non-tumor cell, excess MYC protein expression is removed by the ubiquitin–proteasome system, where MYC is rapidly degraded." (PMID 39858030, 2025). "It inhibited CDK7 in the CAK and TFIIH complexes, leading to reduced transcription in tumor cells, G2/M cell cycle arrest, downregulation of key oncogenes like c-MYC, and ultimately inducing apoptosis in cancer cells." (PMID 40949156, 2025). "As is well known, MYC signaling plays an important role in tumorigenesis, tumor metastasis, and the EMT process." (PMID 40727938, 2025). "Another lncRNA which was shown to stabilize MYC is the lncRNA GLCC1, a glycolysis-associated lnRNA which was found to be overexpressed in CRC tissue compared to adjacent tissue and correlated with tumor progression." (PMID 40126351, 2025). "MYC is involved in the regulation of diverse cellular processes including proliferation, differentiation, and apoptosis, and in some neoplasms, overexpression of MYC has resulted in modulation of the integrated stress response (ISR)." (PMID 40422212, 2025). "Metastatic tumor cells also exhibit high expression of heterogeneous nuclear ribonucleoprotein AB (hnRNPAB), which stabilizes MYC mRNA and promotes neutrophil recruitment at extravasation sites through the secretion of CXCL8." (PMID 40027151, 2025). "MYC gene rearrangement disrupts the metabolic homeostasis of oxidative phosphorylation, leading to uncontrolled tumor proliferation." (PMID 40703518, 2025). "Elevated c-MYC expression promotes tumor progression and therapy resistance, yet c-MYC remains a challenging therapeutic target because of its intrinsically disordered structure and lack of enzymatic activity." (PMID 41349769, 2025). "Mechanistically,azelastine downregulated oncogenic targets (c-MYC, N-cadherin) andupregulated tumor suppressors (E-cadherin, p21), mirroring the effectsof the canonical inhibitor JQ1." (PMID 41152016, 2025). "Our data point to a mechanism involving dysregulation of a broad range of oncogenes such as MYC and tumour-suppressing genes such as TGF-βR2 and SMAD2/3." (PMID 39789354, 2025). "In contrast, previous studies on HPX have mainly focused on its role as a scavenger of labile heme in the tumor microenvironment, where it suppresses cancer progression by limiting heme-induced oncogene activation, such as c-MYC." (PMID 41008813, 2025).
tumor (continued). "The liver morphology of the FHL3 knockdown group was more similar to that of the c-MYC/AKT group, with more fatty changes around the tumor observed by H&E, which is typical of c-MYC/AKT-induced early liver lesions." (PMID 41184244, 2025). "MiR-34b, a tumor suppressor miRNA, plays a crucial role in regulating various genes involved in cellular processes, such as MET, MYC, and NOTCH1, which are implicated in brain injury." (PMID 39129166, 2025). "In contrast, squamocin demonstrates a more pronounced suppression of tumor growth both in vitro and in vivo, exerting significant inhibition on H3K27me3 and MYC, which represent the enzymatic and non‐catalytic functions of EZH2, respectively." (PMID 39823459, 2025). "A cancer hallmark enrichment analysis revealed pathways such as MYC, G2M checkpoint, DNA repair, Notch, AKT, glycolysis, Wnt, TGF-β, EMT, and apoptosis, which are closely linked to tumor stemness, invasion, metastasis, apoptosis, and metabolism." (PMID 40722682, 2025). "The results revealed that depletion of ANKRD10-2 led to decreased migration of tumor cells and decreased the expression levels of MYC target genes." (PMID 40044952, 2025). "In LS and other cancers, dysregulated MYC activity disrupts the delicate balance between tumor-suppressive and oncogenic miRNAs." (PMID 40076599, 2025). "Typically, TdT positivity is considered when 10% or more of tumor cells are positive in immunohistochemistry, but in mature BCLs with MYC rearrangement, this should be interpreted with caution." (PMID 41142614, 2025). "MYC drives glycolysis and lipid biosynthesis, while RTKs facilitate nutrient uptake and energy production, ensuring that the tumor has a steady supply of resources to support rapid proliferation." (PMID 40076599, 2025). "The therapeutic approach aimed at inhibiting LAT1 would offer an opportunity to unleash the functional association between MYC and LAT1, leading to tumor suppression." (PMID 41008653, 2025). "To further examine the effect of MYC on modulating the tumor-promoting activities of LIN28B in EC, we performed transwell assays." (PMID 40740861, 2025). "miR-32-5p demonstrates oncogenic activity in several cancers, while c-MYC oncogene is a well-known driver of cancer, promoting tumor growth by stimulating cell proliferation, blocking apoptosis, and suppressing immune responses." (PMID 40711670, 2025). "Many tumors exhibit “MYC addiction”, wherein sustained MYC activity is essential for tumor maintenance and progression." (PMID 41025936, 2025). "GO terms enriched in MYC-TGFβ exclusive Up genes were negative regulators of neuron differentiation and wound healing, supporting tumor invasive features." (PMID 41415380, 2025). "The compound KI-MS2-008 stabilizes the MAX–MAX homodimers to decrease the expression of MYC target genes and decreases tumor growth in vivo." (PMID 40290126, 2025). "Deregulated expression of the transcription factor c-MYC is well established as a primary driver of diverse tumor types." (PMID 41140443, 2025). "These KAT6 inhibitors were shown to exhibit effective inhibition against both KAT6A and KAT6B, induce cellular senescence, and impede tumor growth in models of MYC‐driven lymphoma and AML." (PMID 41357671, 2025). "Treatment with pegylated arginine deiminase (ADI-PEG 20) to induce arginine depletion markedly impeded tumor growth and enhanced the survival of mice bearing MYC-driven tumors." (PMID 39103941, 2024). "CRISPR/Cas9 can be used to specifically target, and knock-out, mutated or overexpressed oncogenes, such as MYC, KRAS, and EGFR, which drive tumor growth and progression." (PMID 39696697, 2024).
tumor (continued). "Inactivation of MYC has been found to downregulate PD-L1 mRNA and protein expression, enhancing the anti-tumor immune responses in tumor tissues such as hepatocellular carcinoma, acute T-lymphocytic leukemia, and melanoma." (PMID 38762484, 2024). "Reciprocally, MYC requires CDK9 to function as a transcription factor that amplifies transcription to drive tumour growth." (PMID 38001268, 2024). "Among the ‘most wanted’ targets in cancer therapy is the oncogene MYC, which coordinates key transcriptional programs in tumor development and maintenance." (PMID 38321218, 2024). "To further characterize the effect of CENPM on c-MYC HCC tumor development, we silenced CENPM in human HCC cell lines using siRNA (siCENPM)." (PMID 39325536, 2024). "Group 3 MB has been characterized by high expression of the MYC oncogene that enables rapid and aggressive tumor development." (PMID 39048564, 2024). "Polyclonal tumours retain a structure comprising subclones with distinct Apc mutations and transcriptional states, driven predominantly by differences in KRAS and MYC signalling." (PMID 39478206, 2024). "Pertinently, studies elucidate that MYC inhibition reshapes the tumor immune microenvironment in OS by recruiting T lymphocytes and engaging the CD40/CD40L system." (PMID 39431237, 2024). "While CRE induction had no consequences on Vk21153 MM growth, we observed a rapid reduction of M-spikes in Vk22284 tumor-bearing mice, indicating continuous dependency on MYC expression for MM survival." (PMID 38714690, 2024). "The pan-CLK inhibitor SM08502 displays anti-tumor activity in gastrointestinal cancer models, while the potent CLK2 inhibitor T-025 demonstrates anti-tumor efficacy in an allograft model of MYC-driven breast cancer." (PMID 38753413, 2024). "The absence of CD4+ T cells can impede the eradication of tumor cells, and research has demonstrated that inactivation of the oncogene MYC can recruit CD4+ T cells to the tumor site and induce sustained regression of tumors." (PMID 38426090, 2024). "For instance, the transcription factor TFIIH is important in transcription and DNA repair, its CDK7 subunit can regulate the transcription of PD-L1 in a MYC-dependent manner and promote tumor progression." (PMID 38762484, 2024). "Our data point to a mechanism involving dysregulation of a broad range of oncogenes such as MYC, and tumor suppressing genes such as TGF-βR2 and SMAD2/3." (PMID 38410440, 2024). "The results of the differential expression analysis of MYC such as TCGA samples showed that its expression in tumor tissues increased significantly in patients." (PMID 38756697, 2024). "The regulation of anti-tumor cytotoxic cells, such as effector T and NK cells, plays a pivotal role in MYC-related immune evasion." (PMID 39164274, 2024). "For example, the MYC locus – a key regulator of basal-like tumor biology – is commonly amplified in TNBC." (PMID 38721669, 2024). "For example, E3 ubiquitin ligase FBXW7 inhibits cell proliferation in several cancer cells by ubiquitylating MYC, whereas it promotes cell proliferation in certain tumours by p100 degradation." (PMID 38296968, 2024). "Comparatively, NER-high tumours had enrichment of TGFb-pathways, MYC-targets, and other implied in ICI resistance/tumour aggressiveness." (PMID 39129249, 2024). "KEGG pathway analysis indicates that the selected miRNA panel can specifically target SMAD3/CDKN1A/MYC in the TGF-B/SMAD pathway to influence tumor suppression and oncogenesis, as well as target CASP3 in the P13K/AKT pathway to influence apoptosis." (PMID 38256049, 2024). "Studies have indicated that the suppression of MYC expression can effectively reverse tumor progression." (PMID 38383388, 2024). "Here, we demonstrate that KLF16 is essential for BLCA tumor growth and forms a reinforcing regulatory loop with MYC." (PMID 39551759, 2024).
tumor (continued). "All three studies found that MYC amplification was more frequent among HCC patients with high-grade tumours and found a higher prevalence of MYC amplification (19%, 33%, and 50%) compared with the 8% in our study." (PMID 38536546, 2024). "By the same criteria, the onco-signaling genes AURKA, KRAS, and MYC were up-regulated in over 90%, 60%, and 50% of all tumor types, respectively." (PMID 38649187, 2024). "MYC is a transcription factor responsible for modulating cellular proliferation, and orchestrating changes in the tumour microenvironment, including angiogenesis and immune response." (PMID 38505585, 2024). "In agreement with all these results, a longitudinal whole genome sequencing of 37 tumor samples from 8 OS patients who had a poor response to neoadjuvant chemotherapy found that MYC gain/amplification was enriched in treatment-resistant cell populations." (PMID 39596100, 2024). "For example, using CRISPR to inactivate the oncogene MYC has been proposed as a way to halt tumor growth." (PMID 38195537, 2024). "GPER1 activation results in the depletion of MYC/c-Myc, inhibition of tumor proliferation, and enhanced immune recognition by tumor cells." (PMID 39684286, 2024). "We found that oncogenic KRAS suppresses interferon signaling within the tumor cells via MYC, leading to a proinflammatory cascade upon KRAS inhibition." (PMID 39485838, 2024). "Prior evidence has implicated a key role for BRD4 inhibition in multiple tumor states, including G3MB47,48,51,64 among many others, where dominant phenotypic outcomes on transcription were related to disruption of MYC transcription." (PMID 38664416, 2024). "Supporting this idea, combining MYC inhibitors with anti-PD1 therapy effectively reduced tumor volumes in recent murine studies of prostate and pancreatic cancer." (PMID 39596160, 2024). "For instance, amplified MYC signaling can promote tumor proliferation, angiogenesis, and the creation of an immunosuppressive stroma that induces T-cell exclusion and dampens the capacity of antigen presentation." (PMID 38398121, 2024). "Given the rapid tumour progression of our representative MYC-amplified group 3 MB models, the decreased tumour growth and increased survival following one-time treatment with PPHLN1-Mo is encouraging." (PMID 39025928, 2024). "Hsa_circ_0068307, a highly expressed circular RNA in UBC, has been shown to promote tumor growth in vitro and in vivo via sponging miR-147 and promoting the expression of MYC, which is a direct target of miR-147." (PMID 39031286, 2024). "According to previous research, the overexpression of DLX5 can promote tumor cell growth by directly targeting the c-MYC gene." (PMID 38760791, 2024). "More importantly, IGF2BP3 was closely associated with the following five signaling pathways (r > 0.4), that were tumor proliferation signature, G2M checkpoint, PI3K_AKT_mTOR_pathway, MYC targets, and DNA repair related pathways." (PMID 38577615, 2024).